LINC01591 (long independently transcribed non-coding RNA 1591)
Gene: Long non-coding RNA gene on chromosome 8 (135,234,131 to 135,299,719, forward strand). Ensembl gene ENSG00000254083.
Diseases named in the same sentence as LINC01591 in open-access papers:
LINC01591 is named in the same sentence as 1 disease in open-access papers, as found by Europe PMC text mining. Sharing a sentence is not in itself a finding about the gene and the disease.
LINC01591 shares sentences with these, for which no sentence is quoted: breast carcinoma (1 paper).